RN7SL411P (RNA, 7SL, cytoplasmic 411, pseudogene)
Gene: Miscellaneous RNA gene on chromosome 3 (40,209,005 to 40,209,304, forward strand). Ensembl gene ENSG00000265327.
Homologues: Orthologues: chimpanzee Metazoa_SRP (99% identical), macaque Metazoa_SRP (93% identical), dog Metazoa_SRP (74% identical). Paralogues in human: RN7SL1 (82% identical), RN7SL2 (82% identical), RN7SL3 (82% identical), RN7SL220P (82% identical), RN7SL478P (81% identical), RN7SL597P (81% identical), RN7SL126P (80% identical), RN7SL788P (80% identical), RN7SL493P (80% identical), RN7SL743P (80% identical), RN7SL336P (80% identical), RN7SL566P (80% identical), and 704 more.